PPARG (peroxisome proliferator activated receptor gamma)
Diseases named in the same sentence as PPARG in open-access papers (continued):
Sharing a sentence is not in itself a finding about the gene and the disease.
HCMV infection (8 papers, 2015 to 2024). "We here showed that HCMV infection of NSCs associates with increased levels of PPARγ mRNA and protein, although the changes in levels of transcripts appeared much greater than that of the protein." (PMID 27078877, 2016). "Our findings unambiguously demonstrate that HCMV infection causes increased PPARγ levels and activity, increased biosynthesis of 9-HODE, impaired neuronogenesis and enhanced viral replication in NSCs." (PMID 27078877, 2016). "The PPARγ stimulation by these natural ligands results in impaired migration abilities and enhanced viral replication, confirming the important role of PPARγ in HCMV infection." (PMID 35053112, 2022). "The relationships between HCMV infection and PPARs have been explored, given the known role of PPARs, mainly PPARγ isotype, in lipogenesis and inflammation." (PMID 35053112, 2022). "In contrast, in the developing brain, PPARγ activation has deleterious outcomes on neurogenesis, as shown in HCMV infection, and possibly in ZIKV infection." (PMID 34445581, 2021). "Peroxisome proliferator-activated receptor γ (PPARγ) activation is a key effector of CMV infection in cytotrophoblasts and is thought to be involved in the pathophysiology of IUGR." (PMID 33374185, 2020). "Enhanced activity of PPARγ appears to be a common feature of HCMV infection, both in NSCs and cytotrophoblasts." (PMID 27078877, 2016). "Our findings shed a new light on the pathophysiological bases of the neurological outcomes of congenital HCMV infection and on the role PPARγ in neural stem cell and developing brain." (PMID 27078877, 2016). "To assess the pathophysiological relevance of our experiments using NSCs, we next investigated the expression of PPARγ in fetal brain samples from aborted fetuses with congenital HCMV infection (N = 20) or from control subjects (N = 4)." (PMID 27078877, 2016). "The involvement of PPARγ in the pathogenesis of congenital HCMV infection is strongly supported by its pattern of expression in HCMV-infected human brain samples." (PMID 27078877, 2016). "The main result of our study is the identification of PPARγ activation as a molecular determinant of the pathology induced by HCMV infection in neural precursors, in vitro and presumably in vivo." (PMID 27078877, 2016). "Our study provides new insights on the pathogenesis of HCMV infection and paves the way to the discovery of PPARγ-related molecules secreted in the infected brain." (PMID 27078877, 2016). "We observed that HCMV infection dramatically impaired the rate of neuronogenesis and strongly increased PPARγ levels and activity." (PMID 27078877, 2016). "Together, these findings disclose that PPARγ expression is triggered specifically in the brain germinative areas of cases with congenital HCMV infection." (PMID 27078877, 2016). "Based on our previous demonstration that PPARγ activation is an early and key effector of HCMV infection in cytotrophoblast cells, the goal of this study was to gain novel insight about the modalities of PPARγ activation upon infection." (PMID 26171612, 2015). "We previously reported that PPARγ activation in HIPEC impairs cell migration, should PPARγ be activated by rosiglitazone stimulation or HCMV infection." (PMID 26171612, 2015). "The effects of HCMV infection in human immortalized extravillous cytotrophoblasts (HIPEC) were also analyzed, identifying 15-hydroxyeicosatetraenoic acid (15-HETE) and 13-hydroxyoctadecadienoic acid (13-HODE) as predominant PPARγ agonists secreted after HCMV infection." (PMID 35053112, 2022). "In addition, the role of PPARγ in neurogenesis during congenital HCMV infection was deeply studied in neural stem cells from human embryonic stem cells (NSCs)." (PMID 35053112, 2022).
HCMV infection (continued). "Cytomegalovirus infection with low-passage strain VHLE has been shown to induce the activation of PPARγ in cytotrophoblast culture and an immortalized cell line (human invasive proliferative extravillous cytotrophoblast (HIPEC)), leading to impairment of migration and invasiveness." (PMID 33374185, 2020). "We disclosed that HCMV infection strongly increases levels and activity of PPARγ in NSCs." (PMID 27078877, 2016). "We next investigated which ligands accounted for PPARγ activation during HCMV infection of NSC." (PMID 27078877, 2016). "Given that a number of studies have established that peroxisome proliferator-activated receptor γ (PPARγ) is critical for proper brain development, we reasoned that PPARγ may be involved in the impact of HCMV infection on neural progenitor cells." (PMID 27078877, 2016). "HCMV infection has also been shown to inhibit Wnt/β-catenin signaling in dermal fibroblasts and placental extravillous trophoblasts, and this could also account for increased PPARγ activity in HCMV-infected NSCs since Wnt/β-catenin inhibits PPARγ." (PMID 34445581, 2021). "Thus, in EVTs, CMV infection might activate PPARγ and reduce the expression of α1β1 integrin, c-erbB-2, and MMPs, thereby impairing the ability of these cells to invade the uterine vasculature." (PMID 33374185, 2020). "Here, we investigated which ligands account for PPARγ activation, both in the human cytotrophoblast line HIPEC and in placental explants at early steps of HCMV infection." (PMID 26171612, 2015). "We also found increased PPARγ expression in brains of in utero infected fetuses, but not in controls, suggesting that PPARγ is a key effector of HCMV infection also in vivo." (PMID 27078877, 2016).
lymph node metastasis (8 papers, 2010 to 2025). "Disease-free survival (DFS) was associated with lymph node metastasis status and PPARG expression level." (PMID 40303293, 2025). "Previously, we have shown the association of PPARG loss with poor prognostic features in PeCa (advanced clinical and T stage and lymph node metastasis)." (PMID 28122331, 2017). "In their clinicopathological studies, PPARγ mRNA expression level in the patients with esophageal SCC with extensive lymph node metastasis was significantly decreased compared with those with less extensive lymph node metastasis." (PMID 20885923, 2010). "Further analysis revealed that PPARγ, a regulator of FABP1 transcription, was significantly downregulated after lymph node metastasis." (PMID 40694956, 2025). "With larger BC tumor size, the occurrence of axillary lymph node metastasis, and the increase of BC histological grade and TNM stage, PPARG expression level decreased significantly." (PMID 37334066, 2023).
metastatic tumors (8 papers, 2007 to 2024). "On the other hand, clonal mutations in ARNT (OVA_047), NTRK1 (OVA_048), MYH9 (OVA_047) and PPARG (OVA_047), and subclonal mutations in ITGAV (OVA_047) and PTPRT (OVA_003) were all specific to metastatic tumours." (PMID 32099096, 2020). "Among these cases with “WD-like” PPARG expression, one specimen belonged to the patient with multiple relapses and metastatic disease (referred to as M18)." (PMID 32158531, 2020). "PIO was effective in reducing metastatic disease in a tumor model where the effect of PAX8/PPARγ fusion protein is mimicked." (PMID 25866814, 2015). "In cell lines establishedfrom the primary and metastatic tumors of one of these patients, significantly higheramounts of PPARγ transcriptare shown in the cell line derived from the metastatic tumor." (PMID 18784849, 2008). "Targeting FABP12, as opposed to the more broadly-expressed Survivin, Slug or PPARγ, especially in patients with advanced or metastatic tumors, may therefore be of added benefit due to reduced side effects." (PMID 39273616, 2024).
overnutrition (8 papers, 2007 to 2023). An imbalanced nutritional status resulting from excessive intake of nutrients. "Our investigation of CD36, PPARγ, and mitochondrial DAMPs provides new insight into the crosstalk between metabolism and inflammation in the progression of overnutrition-caused liver fibrinogenesis." (PMID 31652636, 2019). "The expression of PPARγ is induced in response to overnutrition in the liver." (PMID 29743883, 2018). "This study shows that overnutrition suppresses the phosphorylation of AMPK and TBC1D1, augmenting the level of GTP-bound Rab2A and increasing the stability of PPARγ, which ultimately promotes the hepatic accumulation of lipids." (PMID 35061665, 2022).
pneumonia (8 papers, 2019 to 2025). An acute, acute and chronic, or chronic inflammation focally or diffusely affecting the lung parenchyma, caused by an infection in one or both of the lungs (by bacteria, viruses, fungi, or mycoplasma.). "Long-term (~1–5.5 y) use of PPARγ agonists increases the risk of pneumonia or lower respiratory tract infection significantly, some of which result in hospitalization, disability, or death." (PMID 35288651, 2022). "A commercially tested peptide inhibitor targeting JNK-MAPK, could block these PTMs of PPARγ, restore IL-10 expression, and improve the survival of murine pneumonia models." (PMID 37670258, 2023). "Moreover, LOX-1+ neutrophils exhibited higher expression of PPARγ, a transcription factor that prevents excessive injury in the lung during pneumonia." (PMID 36264633, 2022).
vitiligo (8 papers, 2017 to 2025). Generalized well circumscribed patches of leukoderma that are generally distributed over symmetric body locations and is due to autoimmune destruction of melanocytes. "Additionally, we identified changes in PPARγ signalling activity throughout developmental stages of human skin and in the pigment-deficient disease state of vitiligo." (PMID 41365874, 2025). "Bioinformatic analyses also confirmed PPARγ modulators as possible innovative approaches for vitiligo." (PMID 40303919, 2025). "These analyses showed that the HF cells from lesional vitiligo skin exhibit significant downregulation in PPARγ pathway activation, relative to heathy controls." (PMID 41365874, 2025). "These analyses revealed that only the HF cell type from vitiligo skin exhibited a significant downregulation in PPARγ pathway activation, relative to heathy controls." (PMID 41365874, 2025). "Notably, therapies targeting metabolic pathways, particularly those involving mitochondrial metabolism, such as the peroxisome proliferator-activated nuclear receptor γ (PPARγ) agonists, are currently being investigated as potential treatments for vitiligo." (PMID 40303919, 2025). "Furthermore, similar to precedent studies, we demonstrated that PPARγ agonist enhanced glycolysis and reverted the myofibroblast phenotype, characteristic of vitiligo dermal components." (PMID 36429011, 2022). "Therefore, we conducted a study to evaluate the effect of Pioglitazone (PGZ), a Peroxisome proliferator-activated receptor-γ (PPARγ) agonist, on cells from pigmented vitiligo skin." (PMID 36429011, 2022).
acute promyelocytic leukemia (7 papers, 2011 to 2022). An aggressive form of acute myeloid leukemia (AML), characterized by arrest of leukocyte differentiation at the promyelocyte stage, due to a specific chromosomal translocation t(15;17) in myeloid cells. "In promyelocytic leukemia (APL) driven by the PML-RAPα oncoprotein, it was found that PML-RAPα can reduce the expression of PPARγ." (PMID 36106108, 2022).
amyloid (7 papers, 2013 to 2024). "Pre-clinical and clinical studies have shown that TZDs, a group of PPARγ agonists, can reduce Aβ generation and release, improve learning and memory, and decrease amyloid pathology in a time- and dose-dependent manner." (PMID 39185170, 2024). "In some humans with early AD and in mouse models for AD-like amyloidosis, impaired memory can be improved with PPARγ activation." (PMID 25540218, 2015). "Activation of the PPARγ axis improves hippocampal-related memory in some humans, with early AD and mouse models for AD-like amyloidosis." (PMID 25540218, 2015). "Aβ pathology resulted in altered functional properties of these DG neurons, and PPARγ agonism restored most of these, suggesting that PPARγ signaling promotes a global program aiming at normalizing DG function during AD amyloidosis." (PMID 25540218, 2015). "However, an elucidation of intrinsic and passive properties for distinct cell subtypes in the DG of an AD amyloidosis model, as well as following cognitive enhancement with PPARγ agonism, remains elusive." (PMID 25540218, 2015). "Interestingly, therapeutic application of the PPARγ agonists, pioglitazone, has been demonstrated to skew microglia from M1 to the M2 phenotype, reduce amyloid plaque burden, and improve cognitive deficits in the APP/PS1 mouse model of AD." (PMID 24244499, 2013).
aneurysm (7 papers, 2012 to 2025). Bulging or ballooning in an area of an artery secondary to arterial wall weakening. "Proinflammatory environment in aneurysms was shown by significant upregulation of M-CSF and PPARγ but associated with downregulation of chemokines." (PMID 26539497, 2015). "The activators of PPARG, such as rosiglitazone and pioglitazone, have been shown to alleviate the development and rupture of Ang II-induced aneurysms in mouse models." (PMID 35990982, 2022). "Alternatively, the M2 phenotype is stimulated by other factors, such as peroxisome proliferator-activated receptor γ (PPARγ), or pioglitazone, an agonist of PPARγ, which resulted in a protective effect against aneurysms in mice." (PMID 34200256, 2021). "Despite this difference, our aneurysm samples show a higher level of M-CSF, PPARγ, and mononuclear cells than in controls, thereby indicating a specific modulation of vascular remodeling." (PMID 26539497, 2015).
bronchopulmonary dysplasia (7 papers, 2009 to 2023). Bronchopulmonary dysplasia is a chronic respiratory disease that results from complications related to lung injury during the treatment of infant acute respiratory distress syndrome in low-birth-weight premature infants or from abnormal lung development in older infants. "The underlying pathophysiology of bronchopulmonary dysplasia includes a macrophage-mediated host response orchestrated by anti-inflammatory peroxisome proliferator-activated receptor gamma (PPARγ) and anti-oxidant nuclear factor (erythroid-derived 2)-like 2 (Nrf2)." (PMID 28886148, 2017). "Thiazolidinediones (TZDs) are potent PPARγ agonists that have been shown to attenuate alveolar simplification after prolonged hyperoxia in term rodent models of bronchopulmonary dysplasia." (PMID 35890402, 2022). "For example, the higher levels of miR-27b-3p in pseudoglandular male lung is notable because PPARγ agonists have been proposed for prevention and treatment of bronchopulmonary dysplasia (BPD), a disease more common in males." (PMID 35480332, 2022). "Administration of PPARγ agonists (as therapeutic treatment in bronchopulmonary dysplasia) inhibits the canonical WNT/TGF-β pathway and stimulates PPARγ activity." (PMID 35740412, 2022).
cardiomyopathy (7 papers, 2017 to 2025). A disease of the heart muscle or myocardium proper. "CR reduced PPARγ levels, consequently preventing the initiation of the cascade that leads to lipotoxicity that participates in the cardiomyopathy process." (PMID 31100876, 2019). "The review identified key gene variants affecting athletic performance: endurance (AMPD1, PPARGC1A), power (ACTN3, NOS3), strength (PPARG), and injury susceptibility (COL5A1, MMP3), while also examining inherited conditions like cardiomyopathies (MYH7, MYBPC3)." (PMID 40724525, 2025).
cholangiocarcinoma (7 papers, 2008 to 2025). A carcinoma that arises from the intrahepatic biliary tree (intrahepatic cholangiocarcinoma) or from the junction, or adjacent to the junction, of the right and left hepatic ducts (hilar cholangiocarcinoma). "There is a positive feedback loop between FABP4 and PPARG in facilitating fatty acid uptake and oxidation in cholangiocarcinoma lymph node metastasis." (PMID 40604951, 2025). "There is a positive feedback loop between FABP4 and PPARG in promoting fatty acid uptake and oxidation in lymph node metastasis of cholangiocarcinoma." (PMID 40604951, 2025). "miR-130a-3p also regulates Gemcitabine resistance via targeting PPARG in Cholangiocarcinoma." (PMID 34657551, 2021).
esophageal squamous cell carcinoma (7 papers, 2010 to 2022). Esophageal squamous cell carcinoma (ESCC) is a type of esophageal carcinoma (EC) that can affect any part of the esophagus, but is usually located in the upper or middle third. "Efatutazone, a third-generation PPARγ agonist, has been reported to inhibit esophageal squamous cell carcinoma (ESCC) cell proliferation in vitro and in vivo through increased p21Cip protein levels via inactivation of Akt." (PMID 29599799, 2018). "PPARγ is expressed in normal esophageal squamous epithelium, esophageal squamous intraepithelial neoplasia, and esophageal squamous cell carcinoma." (PMID 29483923, 2018). "Since PPARγ is highly expressed in the esophageal cells, PPARγ agonist drugs, such as rosiglitazone, are found to decrease the growth, proliferation, invasion, and metastasis of the cell lines of the esophageal squamous cell carcinoma and act in a certain dose-dependent manner." (PMID 29483923, 2018). "In esophageal squamous cell carcinoma with various differentiation levels, the expression of PPARγ mRNA and protein is also different, and it has proved that the degree of differentiation of tumor cells is inversely correlated to PPARγ mRNA and protein expression." (PMID 29483923, 2018). "It is found that the expressions of PPARγ mRNA and protein in the esophageal squamous intraepithelial neoplasia and esophageal squamous cell carcinoma are significantly lower than those of the normal esophageal squamous epithelium and are correlated with the cellular differentiation levels." (PMID 29483923, 2018). "In regard to human esophageal squamous cell carcinoma (SCC), PPARγ has been found to be expressed in human SCC cell lines such as TE-1, TE-2, TE-5, TE-7, TE-8, TE-9, and TE-10." (PMID 20885923, 2010).